MGMT (O-6-methylguanine-DNA methyltransferase)
Diseases named in the same sentence as MGMT in open-access papers (continued):
Sharing a sentence is not in itself a finding about the gene and the disease.
glioblastoma (continued). "In line with this, several studies demonstrated that pharmacological inhibition of gap junctions sensitizes primary MGMT-methylated human glioblastoma cell populations to TMZ-mediated toxicity." (PMID 35045869, 2022). "Series of phase III clinical trials displayed disappointing results of PD⁃1 in glioblastoma, including the OS of recurrent glioblastoma in CheckMate-143, OS of newly diagnosed MGMT⁃unmethylated glioblastoma, PFS of newly diagnosed MGMT⁃methylated glioblastoma." (PMID 36091179, 2022). "Exposure to the MGMT gene leads to a decrease in the precipitation of the MGMT protein, and subsequently glioblastoma cells restore sensitivity to temozolomide." (PMID 35684445, 2022). "O6-methylguanine DNA methyltransferase (MGMT) promoter methylation is a prognostic factor for glioblastoma." (PMID 36291588, 2022). "O6-methylguanine (O6-MeG)-DNA methyltransferase (MGMT) methylation status is a predictive factor for alkylating treatment efficacy and glioblastoma patients, and its prognostic role is still unclear." (PMID 35626029, 2022). "The study confirmed no adverse effects after the use of MET, confirming its safety and tolerability and validating previous results on favorable outcomes of glioblastoma patients, particularly those with low methylation levels of MGMT (NCT02780024)." (PMID 35326565, 2022). "It is well-established that glioblastoma patients with promoter methylation of the DNA repair enzyme O6-methylguanine-DNA methyltransferase (MGMT) derive more benefit from treatment with temozolomide." (PMID 36091179, 2022). "In contrast, TMZ chemotherapy, possibly combined with lomustine, appears to be a useful alternative for glioblastoma with the methylated MGMT promoter." (PMID 35563629, 2022). "Methylation-specific PCR (MSP) is the golden standard for MGMT methylation assessment in glioblastomas." (PMID 35806153, 2022). "Only intensification of chemotherapy in a molecular subset of glioblastomas exhibiting methylation of the O-6-methylguanine-DNA methyltransferase (MGMT) promoter has shown moderate improvement in prognosis." (PMID 35725846, 2022). "Further on, in a similar patient population, with newly diagnosed glioblastoma and treated with radiotherapy plus temozolomide, MGMT methylation status has been shown to be strictly correlated to timing and pattern of recurrence." (PMID 35806153, 2022). "There have been many reports that used pyrosequencing and analyzed the MGMT promoter methylation status cutoff value for predicting the prognosis of glioblastoma patients." (PMID 35397757, 2022). "VERTU was a randomized non-comparative phase 2 trial involving 125 adults with newly diagnosed MGMT-unmethylated glioblastoma." (PMID 35205750, 2022). "MGMT-methylated tumors occurred mainly in the parietal lobe, whereas unmethylated glioblastomas were localized in the insula." (PMID 35330402, 2022). "Previous studies showed that patients with MGMTmet with grade II or III glioma or glioblastoma have a longer overall survival compared with those with unmethylated MGMT promoter (MGMTunmet)." (PMID 36711137, 2022). "We evaluated glioblastoma patients with an assessment of MGMT methylation status by pyrosequencing from nine Italian centers." (PMID 35626029, 2022). "In phase I, patients with the first relapse of MGMT-methylated glioblastoma are screened for the trial." (PMID 35045869, 2022). "Gliomas with methylated MGMT promoters display less edema than MGMT promoter unmethylated glioblastoma." (PMID 36289752, 2022). "MGMT promoter methylation is the key mechanism of MGMT gene silencing and predicts a favorable outcome in patients with glioblastoma who are exposed to alkylating agent chemotherapy." (PMID 35158753, 2022).
glioblastoma (continued). "MGMT is already in clinical use for elderly glioblastoma patients, despite several reports of intratumour heterogeneity and uncertainty regarding the optimal threshold." (PMID 36428772, 2022). "The companion phase 3 CheckMate 498 trial was designed to compare OS for new unmethylated MGMT glioblastoma patients treated with either nivolumab + RT vs. temozolomide + RT." (PMID 36011015, 2022). "It is widely accepted that glioblastoma patients with MGMT promoter methylated are sensitive to temozolomide and suitable for TMZ chemotherapy." (PMID 36727078, 2022). "It was described that CpG methylation in the MGMT promoter region can be predictive for therapy outcome coupled with overall survival of glioblastoma patients." (PMID 35180887, 2022). "Studies show modest benefits of temozolmide treatment in patients with methylated MGMT in colorectal cancer and patient-derived xenograft (PDX) models of glioblastoma show high expression of MGMT linked to active enhancers, despite promoter methylation." (PMID 35326684, 2022). "In a comparative literature review and meta-analysis, we showed that the MGMT promoter methylation did indeed change significantly in more than 20% of glioblastoma patients." (PMID 35563629, 2022). "Among 3 O6-methylguanine–DNA methyltransferase (MGMT)-evaluable glioblastomas, 2 were unmethylated and 1 was MGMT-methylated." (PMID 35740557, 2022). "The first investigations for biologically-driven individualization of target volumes for glioblastoma patients focused on MGMT status—in two studies, MGMT methylation was significantly correlated with more out-of-field recurrences." (PMID 36230481, 2022). "Prospective randomised trials of glioblastoma patients for radiotherapy versus alkylating agent chemotherapy have demonstrated DNA methylation of MGMT is a clinically useful predictive biomarker to stratify patients, rather than just prognostic." (PMID 35326684, 2022). "In the 194 tumor cohort, CD73 expression was slightly lower in recurrent/residual tumors as compared to primary lesions and in IDH-WT glioblastoma with an unmethylated (unsilenced) MGMT promoter compared to ones with MGMT promoter methylation." (PMID 35973991, 2022). "Comprehensive biomarker discovery is underway, and we await the outcome of a complementary trial Alliance A071102 (NCT02152982) for patients with newly diagnosed MGMT-methylated glioblastoma." (PMID 35205750, 2022). "Overall, knowledge of MGMT methylation status is critical for clinicians to better personalize the care of glioblastoma patients." (PMID 35806153, 2022). "In another Phase II study, the addition of the PD-L1 inhibitor durvalumab to standard therapy moderately prolonged survival in patients with newly diagnosed MGMT-unmethylated glioblastoma compared with historical controls: 15.1 vs. 12.7 months, respectively." (PMID 35406398, 2022). "This study aimed to evaluate survival in patients with primary glioblastoma concerning O6-methylguanine–DNA methyltransferase (MGMT) promoter methylation and other clinical factors." (PMID 36009577, 2022). "Using a deep learning pipeline to predict MGMT status in glioblastoma patients automatically showed good predictive performance." (PMID 35330402, 2022). "The glioblastoma cells typically have elevated levels of O6-methylguanine DNA methyltransferase (MGMT), a DNA repair protein that facilitates acquired drug resistance." (PMID 36153528, 2022). "MYC for cervical cancer, IDH1 for hepatic cirrhosis, MGMT for glioblastoma and CCND1 for anaplastic thyroid cancer were identified as genes with prognostic importance using survival analysis." (PMID 35001007, 2022). "An important predictive marker for the response towards treatment with alkylating chemotherapy is the MGMT promotor methylation, which is present in about 45% of glioblastoma and can help in clinical decision making." (PMID 35955806, 2022).
glioblastoma (continued). "MGMT promoter methylation status is an important marker for therapeutic response to temozolomide in glioblastoma patients and has an important predictive role in elderly glioblastoma patients." (PMID 35626029, 2022). "We investigated how progression-free survival (PFS) and overall survival (OS) in older patients with IDH wild-type glioblastoma were influenced by concomitant radio-chemotherapy and MGMT promotor methylation status in real-life settings." (PMID 36551664, 2022). "Each case had data from a 447-gene targeting exome sequencing assay, chromosomal copy-number analysis, and O6-methylguanine-DNA methyltransferase (MGMT) promoter analysis; MGMT silencing is predictive of glioblastoma sensitivity to alkylating chemotherapy." (PMID 35973991, 2022). "The expression and promoter methylation of MGMT in glioblastoma can serve as a predictive biomarker for the response to temozolomide (an alkylating agent) treatment." (PMID 35328658, 2022). "Despite the success in correlating O-6-methylguanine-DNA-methyltransferase (MGMT) methylation with survival in glioblastoma patients treated with alkylating agents, the clinical utility of other biomarkers is limited." (PMID 36135196, 2022). "O-6-methylguanine-DNA methyltransferase (MGMT) was identified as an immediate putative target of miR-370-3p and increased expression of miR-370-3p restored glioblastoma sensitivity to TMZ, affecting MGMT expression." (PMID 35330864, 2022). "In Germany, the alternative CeTeG-regimen, with a combination of CCNU and temozolomide, is used for the treatment of young patients with MGMT-promotor methylated glioblastoma." (PMID 35955806, 2022). "The population of glioblastoma patients with MGMT promoter methylation was reported to be 25–47% in recent randomized clinical trials." (PMID 35397757, 2022). "We performed a large, multicenter, retrospective study to assess the prognostic role of MGMT promoter methylation values by PSQ in glioblastoma." (PMID 35626029, 2022). "Previous molecular characterization of NULU and ZAR patient-derived glioblastoma cell lines revealed the unmethylated profile of the MGMT gene promoter and, consequently, a pharmaco-resistance phenotype to standard chemotherapy with TMZ." (PMID 35458581, 2022). "We, and others, have demonstrated that the MGMT methylation status differs spatially within glioblastoma tumours." (PMID 36428772, 2022). "In over 40% of primary glioblastomas, and over 70% of secondary glioblastomas, MGMT is epigenetically inactivated by hypermethylation of the 5’-CpG island." (PMID 35806212, 2022). "Parenthetically, glioblastoma heterogenicity can also affect the prognostic/predictive value of the MGMT gene methylation status." (PMID 35806153, 2022). "As an example, a real-time, methylation-specific PCR assay has been utilized in a trial designed to correlate, in newly diagnosed glioblastoma patients, the responses to dose-dense temozolomide with MGMT methylation." (PMID 35806153, 2022). "MGMT methylation status is routinely investigated in glioblastoma utilizing primers, decisively validated in clinical trials, interrogating, within exon 1, 9 CpG sites." (PMID 35806153, 2022). "For instance, alterations in hypermethylation of O6-methylguanine DNA methyltransferase (MGMT) in glioblastoma can be useful indicators of chemotherapy response." (PMID 36686824, 2022). "Glioblastoma cells are able to develop drug resistance to temozolomide due to the O6-methylguanine-DNA-methyltransferase (MGMT) gene." (PMID 35684445, 2022). "pCas9/MGMT downregulated the expression of MGMT to sensitize glioblastoma cells to temozolomide, enhancing the therapeutic effects of temozolomide in glioblastoma." (PMID 35918694, 2022). "The role of MGMT methylation status as a predictive marker of temozolomide response is well established in patients with glioblastoma of all ages." (PMID 35049706, 2022).
glioblastoma (continued). "This study confirms the major treatment-independent prognostic factors of age and tumour MGMT promotor methylation, and supports the role of debulking surgery and chemoradiotherapy in newly diagnosed glioblastoma." (PMID 35804940, 2022). "Accordingly, nCATS has been successful in simultaneously detecting methylation of the MGMT gene and mutations in Isocitrate Dehydrogenase (IDH) 1/2 genes, these are necessary for better narrowing glioblastoma diagnosis." (PMID 35806153, 2022). "Patients with glioblastomas with ≥16% methylation of the MGMT promoter region display improved survival compared with those with tumors with <16% methylation." (PMID 35804921, 2022). "Western blot analysis of long-term treated glioblastoma cells revealed the decrease of MGMT protein for both ZAR and NULU cell lines (respectively)." (PMID 35458581, 2022). "Many factors impact survival in patients with glioblastoma, including age, Karnofsky Performance Status, postoperative chemoradiation, IDH1/2 mutation status, MGMT promoter methylation status, and extent of resection." (PMID 35156038, 2022). "Two randomized clinical trials supported the importance of cancer therapies stratification based on MGMT gene promoter methylation status in elderly glioblastoma patients." (PMID 35626029, 2022). "Methylated MGMT has been known for a long time to be a favorable prognostic marker in glioblastomas and predicts their response to alkylating chemotherapy." (PMID 35558510, 2022). "Due to the inclusion criteria, patients were generally diagnosed with an IDH 1/2 wildtype glioblastoma, and 32% (n = 19) showed a promoter methylation of the MGMT gene." (PMID 35692752, 2022). "According to WHO CNS 2016 classification, NULU and ZAR are IDH1 wild-type glioblastoma cell lines with unmethylated MGMT promoter genes, leading to a drug-resistant phenotype." (PMID 35458581, 2022). "Accordingly, regorafenib is currently under investigation in patients with newly diagnosed glioblastoma with unmethylated MGMT promoter in the GBM AGILE trial." (PMID 35716310, 2022). "For example, patients with secondary glioblastoma have the best response to temozolomide (standard of care for glioblastoma in the first-line setting) if the tumor is IDH-mutated and MGMT-methylated." (PMID 35406550, 2022). "MGMT methylation was only determined from untreated specimen because methylation status is largely consistent in primary and recurrent glioblastoma." (PMID 35183162, 2022). "Glioblastoma is resistant to the chemotherapeutic molecule temozolomide (TMZ) by expression of O6-methylguanine-DNA methyltransferase (MGMT), despite TMZ having BBB-penetrative properties." (PMID 36365214, 2022). "We therefore generated LDBS data across the MGMT promoter region as a “gold standard” in 69 glioblastoma and 11 anaplastic astrocytoma samples." (PMID 35180887, 2022). "Low expression or promoter hypermethylation of MGMT is correlated with a favorable outcome of glioblastoma patients who received temozolomide, because these cancer cells are unable to efficiently repair temozolomide-induced alkylations." (PMID 35328658, 2022). "Methylation of MGMT promoter is more commonly seen in secondary glioblastomas as compared to primary glioblastomas." (PMID 36185622, 2022). "A phase 3 CheckMate-498 study comparing radiotherapy with temozolomide and radiotherapy with nivolumab did not meet the primary endpoint of overall survival in patients with newly diagnosed MGMT-unmethylated glioblastoma patients." (PMID 35397757, 2022). "In glioblastoma treatment, ginsenoside Rg3 inhibited O6-methylguanine-DNA-methyltransferase (MGMT) by regulating the Wnt/β-catenin pathway and significantly enhanced the sensitivity of glioma to TMZ chemotherapy." (PMID 35684449, 2022). "The aim of our study was to determine a threshold of quantitative MGMT methylation status for better survival among patients with IDH wildtype glioblastomas." (PMID 35804921, 2022).
glioblastoma (continued). "It is very useful to establish different approaches in glioblastoma patients based on their MGMT status, and to introduce MGMT biomarker assessment into routine clinical practice." (PMID 35806478, 2022). "The status of a DNA repair protein called MGMT is a prognostic marker in patients with glioblastomas, the most frequent malignant brain tumor." (PMID 35804921, 2022). "The survival time and progression-free survival of glioblastoma patients with IDH mutations alone was shorter than that of patients with IDH mutations and MGMT methylation." (PMID 35806478, 2022). "In MGMT unmethylated glioblastoma, on the other hand, the benefit of temozolomide is at best limited, rendering this effect negligible." (PMID 35704157, 2022). "MGMT testing to select patients with glioblastoma for clinical trials is feasible, and withholding TMZ from patients without MGMT promoter methylation is justified in this context." (PMID 36003766, 2022). "In this study, combined MFA/TMZ therapy will be administered (orally) in patients with first relapse of MGMT-methylated glioblastoma." (PMID 35045869, 2022). "Conclusions partially disproven by three comparative studies finding that MGMT methylation status assessed by pyrosequencing is, indeed, more reliable for predicting the survival of glioblastoma patients." (PMID 35806153, 2022). "The best predictor of sensitivity to TMZ in patient-derived xenograft models of glioblastoma was found to be a combination of low MGMT activity and intact MMR." (PMID 36009577, 2022). "MGMT promoter methylation is found more often in secondary glioblastomas than in primary glioblastomas (75% versus 36%)." (PMID 35806478, 2022). "One of the mechanisms of glioblastoma resistance to TMZ involves O6-methylguanine DNA methyl transferase (MGMT), a suicide enzyme that allows the direct repair of the lesions caused by TMZ, through the removal of a methyl group in position O6 of guanine." (PMID 35053532, 2022). "The concordance between MSP and pyrosequencing has been reported to be high, at least in assessing MGMT methylation in glioblastomas." (PMID 35806153, 2022). "O6-methylguanine (O6-MeG)-DNA methyltransferase (MGMT) methylation status is a predictive factor for alkylating treatment efficacy in glioblastoma patients, but its prognostic role is still unclear." (PMID 35626029, 2022). "Overall, the results of these clinical studies have led to the recommendation of investigating MGMT methylation status in all patients with newly diagnosed glioblastomas." (PMID 35806153, 2022). "This study showed that dose escalation guided by DOPA PET appeared to be safe, and it significantly improved progression free survival in MGMT un-methylated glioblastoma and overall survival in MGMT methylated patients." (PMID 36612093, 2022). "ATM inhibition exhibited slight sensitization effects towards temozolomide treatment in MGMT low expressing glioblastoma cells, thus encouraging further characterization." (PMID 35440003, 2022). "MGMT is epigenetically inactivated by gene promoter methylation (methylated MGMT) in about 45% of patient-derived glioblastoma and MGMT gene methylation status remains the most significant predictive biomarker for better outcomes after CRT." (PMID 33850305, 2022). "Here, we characterize a unique subgroup of CSCs in MGMT-null experimental glioblastoma, identifying EGF + TMZ therapy as a potential strategy to overcome cellular quiescence and TMZ resistance, likely endowed by deficient EGFR signaling." (PMID 36316307, 2022). "We aimed to investigate how progression-free survival (PFS) and OS in older patients with IDH wild-type glioblastoma are impacted by concomitant radio-chemotherapy and MGMT promotor methylation status in real-life settings." (PMID 36551664, 2022).